GSK3B (glycogen synthase kinase 3 beta)
Diseases named in the same sentence as GSK3B in open-access papers (continued):
Sharing a sentence is not in itself a finding about the gene and the disease.
pancreatic cancer (continued). "GSK-3β influences NF-κB-mediated gene transcription in pancreatic cancer cells at a point distal to the IκB kinase complex." (PMID 21110852, 2010). "Genetic depletion of GSK-3β by RNA interference suppresses basal NF-κB transcriptional activity, leading to decreased pancreatic cancer cell proliferation and survival." (PMID 21110852, 2010). "Recent evidences suggest that GSK-3β positively regulates human pancreatic cancer and leukaemia cell survival in part through regulation of nuclear factor (NF-κB)-mediated expression of anti-apoptotic molecules." (PMID 19920820, 2009). "Consistent with previous findings in pancreatic cancer and leukaemia cells, we found that pharmacologic inhibition of GSK-3β resulted in depletion of nuclear GSK-3β from the renal cancer cells' nuclei by 24 h of AR-A014418 treatment." (PMID 19920820, 2009). "Recently, we have shown aberrant nuclear accumulation of GSK-3β in pancreatic cancer and leukaemia cells." (PMID 19920820, 2009). "Recently, we have shown that only active form of GSK-3β is detectable in the nucleus of pancreatic cancer cells." (PMID 19920820, 2009). "Pharmacological or siRNA mediated inhibition of GSK-3β has been shown to reduce NF-κB mediated gene transcription and inhibit the growth of cancers that show high NF-κB activity including pancreatic cancer." (PMID 19405981, 2009). "Our findings are supported by previous studies showing nuclear overexpression of GSK-3β in pancreatic cancer and CLL." (PMID 19920820, 2009). "Additionally, the effects of STYK1-derived peptides that target its interaction with GSK3β and β-catenin were also investigated in pancreatic cancer mice models." (PMID 40588478, 2025). "It was shown that GSK3β inhibition disrupts NFκB-mediated gene transcription in pancreatic cancer." (PMID 40408503, 2025). "GSK‐3β could enhance the efficacy of chemotherapy and radiation therapy in pancreatic cancer treatment." (PMID 39632551, 2024). "Importantly, we discuss the central role of GSK3β as a molecular hub that mechanistically connects chemoresistance, tumor cell invasion, and stemness in pancreatic cancer." (PMID 38318525, 2024). "Here, we briefly discuss the prospective involvement of GSK3β in the pancreatic cancer TME." (PMID 38318525, 2024). "Our findings revealed that LRRFIP1 could promote pancreatic cancer progression through the AKT/GSK-3β/β-catenin signaling axis." (PMID 38634978, 2024). "Genetic or pharmacological inhibition of AURKA significantly inhibited GSK3β S9 phosphorylation in pancreatic cancer cells, suggesting that GSK3β might indeed act as a downstream target of AURKA in necroptosis." (PMID 39334449, 2024). "These underscores GSK‐3β as a promising target for pancreatic cancer therapy." (PMID 39632551, 2024). "Our previous studies on gemcitabine-unresponsive pancreatic cancer and temozolomide-resistant glioblastoma cells have indicated that GSK3β enhances tumor cell migration and invasion via the focal adhesion kinase (FAK), Rac1, and c-Jun N-terminal kinase (JNK)-mediated pathway." (PMID 38318525, 2024). "The nuclear localization of GSK3β has been related to a mesenchymal phenotype in triple negative breast cancer and pancreatic cancer, and the increase in its expression with poor prognosis in urothelial carcinoma renal, pancreatic, leukemia and triple negative breast cancer." (PMID 38528037, 2024). "Taken together, the findings suggest that LRRFIP1 may influence cell proliferation and mobility in pancreatic cancer through regulation of AKT/GSK-3β/β-catenin signaling pathway." (PMID 38634978, 2024). "GSK‐3β is commonly overexpressed in various types of cancer such as pancreatic cancer." (PMID 39632551, 2024). "Finally, phase I and II clinical trials of GSK-3β inhibitor are being conducted for pancreatic cancer and gliomas." (PMID 37366889, 2023).
pancreatic cancer (continued). "To characterize the role of nuclear GSK-3β in pancreatic cancer development, we generated a pancreas-specific nuclear-targeted GSK-3β expression model by inserting a GSK-3β cDNA transgene containing an HA tag and a nuclear localization signal sequence into the Rosa26 locus." (PMID 35646902, 2022). "In addition to the effect of GSK-3β on proliferation and inhibition of apoptosis, GSK-3β phosphorylates/inhibits Cyclase-Associated Protein 1 (CAP-1), leading to increased migration and invasion of pancreatic cancer cells." (PMID 36430630, 2022). "Furthermore, a previous report indicating the role of DEPDC1B in pancreatic cancer development through targeting the Akt/Gsk3b/Snail pathway also provides support for the alleviation of DEPDC1B overexpression-induced effects by CDK1 knockdown." (PMID 36568241, 2022). "According to reports, the combination of GSK-3β inhibitors with chemotherapy is strategically poised to be a promising approach to overcome the emergence of early drug resistance or to overcome chemoresistance in advanced and metastatic pancreatic tumors." (PMID 35327583, 2022). "GSK-3β is a key regulator of the NF-κB transcription factor responsible for the expression of genes that regulate proliferation, apoptosis, inflammation, angiogenesis, invasion, and chemo-resistance in pancreatic cancer cells." (PMID 36430630, 2022). "To further verify that COL11A1 promoted the EMT process in pancreatic cancer cells by activating the AKT/GSK-3β/Snail signaling pathway, we first detected the expression levels of E-cad, N-cad, VIM, and MMP-2/9 in PANC-1 cells with different treatments by Western blotting." (PMID 35327583, 2022). "In this mini-review, we focus on the role of GSK-3β in pancreatic cancer." (PMID 36430630, 2022). "Therefore, COL11A1 enhances the stemness of pancreatic cancer cells by activating the AKT/GSK-3β/Snail signaling pathway." (PMID 35327583, 2022). "Small molecule inhibitors of glycogen synthase kinase-3 beta have demonstrated therapeutic potential in pre-clinical models and are currently being evaluated in early phase clinical trials involving pancreatic cancer patients with interim results showing favorable results." (PMID 34356465, 2021). "Studies have found that adiponectin can inhibit the accumulation of β - Catenin in pancreatic cancer cells by inactivating GSK-3β, thereby reducing the expression of cyclin D1 and leading to arrest of the pancreatic cancer cell cycle in G-G phase, which plays a protective role in pancreatic cancer." (PMID 34485124, 2021). "GSK3β activity has been also correlated to the increased expression and secretion of matrix metalloproteinase-2 and 9, which improved the migratory phenotype of synovial sarcoma, fibrosarcoma, osteosarcoma, and pancreatic cancer cell lines." (PMID 34440861, 2021). "GSK-3β is implicated in cell invasion and metastasis in pancreatic carcinogenesis as its overexpression leads to CXCR4 upregulation and increased MMP-2 expression and results in increased invasiveness of pancreatic cancer cells." (PMID 34356465, 2021). "Furthermore, based on our previous study that FHL3 regulated the Akt/GSK3β/ubiquitin-Snail1|Twist1 pathway to stabilize the EMT-TFs to promote EMT process in pancreatic cancer, we explored the role of FHL3 in the regulation of ubiquitin-mediated EMT." (PMID 34150617, 2021). "YTHDF2 inhibited adhesion, invasion, migration, and Epithelial-Mesenchymal Transition (EMT) through the YAP signal and promoted the proliferation of pancreatic cancer cells through the Serine/threonine-protein kinases/Glycogen synthase kinase 3 beta/Cyclin D1 (AKT/GSK3B/CCND1) pathway." (PMID 33692959, 2021). "Furthermore, the level of aberrant glycogen synthase kinase-3 beta expression in the nucleus is inversely correlated with tumor differentiation and survival in both in vitro and in vivo models of pancreatic cancer." (PMID 34356465, 2021).
pancreatic cancer (continued). "GSK-3β also produced radioresistance of pancreatic cancer cells by a β-catenin dependent mechanism." (PMID 33068388, 2020). "This is supported by the previous finding that IL-33 ligating to its receptor could inhibit GSK-3β that normally regulates the proliferation and survival of pancreatic cancer cells 34, finally leading to attenuation of cancer progression." (PMID 33046978, 2020). "Upregulation of miR-940 suppresses GSK3β and sFRP1 and could promote pancreatic carcinoma proliferation and invasion." (PMID 32019170, 2020). "It is reported that, additionally, GSK-3β inhibition may induce autophagy in human pancreatic cancer cells and in prostate cancer cells." (PMID 31057395, 2019). "The results indicate that GSK‐3β activity plays a key role in the antitumor effect of FUT‐175 in pancreatic cancer cells, and regulation of GSK‐3β by PP2A inhibition could be a novel therapeutic approach for pancreatic cancer." (PMID 29863120, 2018). "It was reported that the inhibition of Gsk3β could increase the sensitivity to gemcitabine in pancreatic cancer PANC-1 cells." (PMID 28076327, 2017). "However, GSK-3 is overexpressed in various cancer conditions such as colon, liver, ovarian, and pancreatic tumors and GSK-3β downregulation inhibits pancreatic cancer growth, angiogenesis, and vascular endothelial growth factor expression." (PMID 29379583, 2017). "Furthermore, p21cip1 inversely correlated, while p-AKT, p-GSK3β, and nuclear β-catenin positively expression correlated with the expression of miR-629 in pancreatic cancer clinical specimen." (PMID 29072689, 2017). "However, there are contradictory findings that GSK3β mediates tumor promotion and/or GSK3β shows anti-proliferative effects in certain types of tumors including colon and pancreatic cancer." (PMID 27087918, 2016). "Similarly, GSK3β inhibition by AR-A014418 or siRNA in pancreatic cancer cell lines PANC-1 and MIA PaCa-2 reduced activation and nuclear accumulation of NFκB, which resulted in reduced cell growth and colony-formation." (PMID 26560046, 2015). "In addition, a previous study indicated that GSK3β is a potential therapeutic target for pancreatic cancer." (PMID 26556864, 2015). "Overexpression of miR-33a led to a marked downregulation of Pim-3 expression, thereby inhibiting AKT/Gsk-3β/β-catenin signaling, which in turn reduced cell proliferation and increased the chemosensitivity of pancreatic cancer cells to gemcitabine both in vitro and in vivo." (PMID 25971209, 2015). "GSK3β expression and activity are upregulated in pancreatic cancer." (PMID 26213494, 2015). "GSK3β also maintained constitutive NFκB signaling in pancreatic cancer cells." (PMID 26213494, 2015). "In addition, studies have shown that the inhibition of GSK3β attenuates survival and proliferation and induces apoptosis in various types of cancers, such as pancreatic cancer, colorectal cancer and bladder cancer." (PMID 24618715, 2014). "Pancreatic cancer cells showed higher expression and activity of GSK3β than non-neoplastic cells, which were associated with changes in its differential phosphorylation." (PMID 23408967, 2013). "Since UVC significantly inhibited PDGF-BB-induced phosphorylation of Akt, and subsequent glycogen synthase kinase (GSK) 3β, but not p44/p42 MAPK and SAPK/JNK, it is likely that UVC inhibits PDGF-BB-induced migration by suppressing the Akt-GSK3β pathway in pancreatic cancer cells." (PMID 22200892, 2012). "Therefore, our results suggest that UVC inhibits PDGF-BB-induced migration by suppressing the Akt-GSK-3β pathway in pancreatic cancer cells." (PMID 22200892, 2012). "In the last five years, we demonstrated that deregulated expression, phosphorylation of S9 and Y216, and GSK3β activity are distinct features of gastrointestinal cancers including pancreatic cancers and glioblastoma, and that GSK3β sustains the survival and proliferation of these tumor cells." (PMID 24212624, 2011).
pancreatic cancer (continued). "In addition, we highlight an emerging strategy for cancer treatment that targets glycogen synthase kinase 3β (GSK3β), focusing on the effect of its deregulation on pancreatic cancer." (PMID 24212624, 2011). "Modulation of these biological properties by pharmacologic inhibition of GSK3β may sensitize pancreatic cancer cells to standard chemotherapy and radiation." (PMID 24212624, 2011). "GSK3β inhibition may exert indirect anti-tumor actions in pancreatic cancer by modulating metabolic disorder and inflammation." (PMID 24212624, 2011). "Furthermore, it has been shown that GSK-3β is a prosurvival factor in pancreatic tumor cells, partly through its ability to regulate the NF-κB pathway." (PMID 21110852, 2010). "Recent studies have shown that GSK-3β could shuttle from the cytoplasm to the nucleus in pancreatic cancer cell lines and in most poorly differentiated human pancreatic adenocarcinomas, and in human CLL B cells." (PMID 21110852, 2010). "In a recent preliminary study, we found that GSK3β inhibition counteracts tumor invasion and distant metastasis as well as the sphere formation of BxG400 cells, which acquire the highest resistance to gemcitabine established from the gemcitabine-sensitive pancreatic cancer BxPC-3 cells." (PMID 38318525, 2024). "Moreover, in pancreatic cancer and relapsed leukemia, high miR-1246 expression was shown to be associated with drug resistance to 5-fluorouracil and adriamycin by stimulating the miR-1246-AXIN2/GSK-3β-Wnt/β-catenin axis." (PMID 38473390, 2024). "Furthermore, the GSK3B inhibitor could suppress the survival and proliferation of pancreatic cancer cells by attenuating the activity of nuclear factor-kappaB (NF-κB)." (PMID 36743929, 2022). "Pancreatic cancer cells infected with lentivirus containing Cas9 and guide RNA (gRNA) to β-catenin or scrambled were treated with GSK-3β inhibitor SB-732881-H to test whether β-catenin inhibition will rescue PDAC cells from apoptosis induced by the GSK-3β inhibition." (PMID 36430630, 2022). "In addition, Song, Kobayashi and their colleagues reported that PI3K/Akt-inactivated GSK-3β might be the bridge between gal-3 and Wnt signaling in colon and pancreatic cancer." (PMID 25622682, 2015). "Given the roles of STYK1 in the activation of Wnt/β-catenin pathway and pancreatic cancer progression, we evaluated STYK1-driving peptides disrupting STYK1-β-catenin/GSK3β interactions on pancreatic cancer tumorigenesis." (PMID 40588478, 2025). "In pancreatic cancer, YBX1 binds to the GSK3B promoter and promotes the growth of pancreatic ductal adenocarcinoma through the GSK3B/Cyclin D1/Cyclin E1 pathway." (PMID 40799245, 2025). "The dual inhibitors Metavert (inhibitor of GSK3B and HDACs) or CUDC-907 (Phosphoinositide 3-kinases/HDAC Inhibitor) and the HDAC inhibitor AES-135 have shown antitumor activity in mouse models of pancreatic cancer." (PMID 38829622, 2024). "Therefore, elucidating the conceivable contribution of GSK3β to the interaction of PSCs and CAFs with tumor cells may provide a new strategy for targeting the tumor-promoting stroma, thereby combatting chemoresistance in pancreatic cancer." (PMID 38318525, 2024). "Building on this foundation, our study delved into the interaction between the PI3K/AKT/p-GSK3β signaling cascade and S100A16 in pancreatic cancer cells." (PMID 38520747, 2024). "Here, we reveal a requirement for NUAK1 to sustain proliferation of pancreatic cancer cells in vitro and identify a conserved role for NUAK1 in governing centrosome replication through GSK3β‐dependent control of PLK4 protein levels." (PMID 36975767, 2023). "Glycogen synthase kinase-3beta (GSK-3β) is considered as a driver of cancer progression and is a downstream target of PI3K/Akt axis in increasing pancreatic cancer growth and migration." (PMID 35236381, 2022). "The data shows that GSK-3β inhibits LZTR1, leading to a sustained level of K-ras and increased proliferation of the pancreatic cancer cells." (PMID 36430630, 2022).
pancreatic cancer (continued). "In our previous study, we have found that FHL3 participates in Akt/GSK3β pathway-mediated ubiquitination degradation of EMT-TFs, and the E3 ligase RNF146 was firstly reported to interact with FHL3 in pancreatic cancer." (PMID 34150617, 2021). "Inhibition of GSK-3β in pancreatic cancer cells using LiCl, AR-A014418, or SB216763 GSK inhibitors.Targeting GSK-3β by siRNAs in pancreatic cancer cell lines." (PMID 34900673, 2021). "Studies involving pancreatic cancer PDX mice showed that LY2090314, a specific small-molecule GSK-3β inhibitor, led to a reduction in TAK1 and YAP/TAZ protein levels and a consequent decrease in cell proliferation." (PMID 34356465, 2021). "Compared to GSK3β, only a few studies have investigated the tumor-promoting role of GSK3α, another isoform of the GSK3 family, in pancreatic cancer and acute myeloid leukemia." (PMID 32503133, 2020). "We previously demonstrated that GSK3β sustains expression of CDK4, CDK6, and cyclin D1, which results in phosphorylation-dependent inactivation of RB cell cycle regulator, in CRC and pancreatic cancer cells." (PMID 29568361, 2018). "Taken together with all results, we can conclude that MET potentiates the anti-cancer effect of RSV via inhibition of VEGF-B/GSK-3β signaling pathway, then promotes apoptotic effect of RSV to prevent pancreatic cancer progression." (PMID 27705937, 2016). "RSV alone treatment markedly decreased the phosphorylation of GSK-3β at Ser 9, indicating that RSV activated the GSK-3β and served as a potential tumor activator in pancreatic cancer." (PMID 27705937, 2016). "For example, GSK-3β has been shown to regulate the JNK pathway, and its inhibition triggers apoptosis in pancreatic cancer." (PMID 26388612, 2015). "To elucidate the effect of GSK3β on the expression of CXCR4 and MMP-2 in pancreatic cancer cells, we overexpresses GSK3β in PANC1 and SW-1990 cells." (PMID 26213494, 2015). "Here, we investigated the relationship between GSK3β and CXCR4/MMP-2 in pancreatic cancer cells, in order to further characterize the cellular and molecular mechanisms involved in pancreatic cancer." (PMID 26213494, 2015). "To determine the effect of GSK-3 isoforms on NF-κB target gene expression in pancreatic cancer cells, we genetically depleted the expression of GSK-3α and GSK3β, alone or in combination, in PANC-1 cells using RNA interference." (PMID 19405981, 2009). "Collectively, these findings suggest that although NF-κB activity in pancreatic cancer is responsive to both GSK-3 isoforms, GSK-3β is the major regulator." (PMID 19405981, 2009). "Expectedly, the endogenous interaction between GSK3β, β-catenin, and STYK1 was confirmed using immunoprecipitation and immunofluorescence assays with specific antibodies in AsPC-1, PANC-1, SW1990, and MIA-PACA-2 cells and pancreatic cancer patient's tissues." (PMID 40588478, 2025). "LRRFIP1 is essential for pancreatic cancer cell motility and has a minor impact on cell proliferation, which may be mediated by AKT/GSK-3β/β-catenin signaling." (PMID 38634978, 2024). "Furthermore, inhibition of LZTS1 reduced the activity of AKT and its downstream target glycogen synthase kinase 3 β (GSK‐3β) in pancreatic cancer cells, while overexpressed LZTS1 led to upregulated activity of AKT and GSK‐3β." (PMID 39023696, 2024). "Notably, one study reported that YBX1 binds to the promoter of GSK‐3β and induces GSK‐3β expression to promote the growth of pancreatic cancer cells." (PMID 38018586, 2023). "We demonstrate that the proposed anti-cancer roles of GSK-3β are not relevant to pancreatic cancer, and we argue why GSK-3β is, indeed, a very promising therapeutic target in pancreatic cancer." (PMID 36430630, 2022). "In glioma and pancreatic cancer, MYH9 may interact with GSK3β, subsequently triggering the Wnt/β-catenin signaling pathway to facilitate cancer progression." (PMID 36139430, 2022).